ALB (albumin)
Diseases named in the same sentence as ALB in open-access papers (continued):
Sharing a sentence is not in itself a finding about the gene and the disease.
Stroke (continued). "Some studies showed that low ALB levels are associated with poor prognosis in stroke, including all-cause death, heart failure, atrial fibrillation, ventricular arrhythmias, and myocardial infarction." (PMID 40371078, 2025). "In this study, we aimed to assess the association between serum albumin/globulin (A/G) ratio and the prevalence of stroke, using data from the National Health and Nutrition Examination Survey (NHANES)." (PMID 40070476, 2025). "The occurrence of ischemic heart disease, HF, AF, stroke, andvenous thromboembolism is inversely correlated with serum albumin levels,indicating that lower serum albumin levels are associated with a higher incidenceof these conditions." (PMID 40351665, 2025). "Previous observational studies provided evidence about the associations of low serum albumin concentration and the risk factors of stroke." (PMID 38580915, 2024). "The consistency of our results with previous studies reinforces the need for further research into the underlying mechanisms through which serum albumin influences stroke outcomes." (PMID 40655892, 2024). "Previous studies have also shown that higher glycosylated albumin levels were associated with stroke incidence and adverse stroke outcomes." (PMID 39264001, 2024). "Our findings demonstrate that individuals with a genetic predisposition towards low serum albumin levels face an elevated risk of stroke, PHD, AF, and VTE." (PMID 38580915, 2024). "For example, in a systematic review of the diagnostic performance of ischemia-modified albumin in stroke, it was found that the diagnostic performance differed between studies based on the continent of Europe or Asia." (PMID 39528275, 2024). "Previous studies have found that dietary antioxidant intake (including vitamins A, C, E, zinc, selenium, and carotenoids), dietary magnesium intake, and serum levels of albumin and globulin are negatively correlated with stroke mortality risk." (PMID 39483787, 2024). "Against this background, we aimed to conduct primary analyses to determine the association of albumin levels with stroke functional outcomes and mortality including a large prospective cohort of unselected stroke patients with long-term follow-up." (PMID 38794724, 2024). "Prior research has shown that nutritional status indicators, including albumin and body mass index (BMI), were closely associated with the prognosis of stroke patients." (PMID 38699426, 2024). "Glycated albumin (GA) is a relatively novel blood indicator that reflects blood glucose levels 2–4 weeks before stroke onset, and it is closely associated with the development of diabetes." (PMID 39264001, 2024). "On one hand, low albumin levels were not only associated with an increased risk of stroke but also with worse outcomes." (PMID 38699426, 2024). "As such, our data provide further evidence supporting a causal association between serum albumin and the susceptibility to stroke." (PMID 38580915, 2024). "Previous research indicated that higher albumin levels correlated with lower incidence of stroke and fewer complications caused by stroke (such as speech, cognitive, and motor impairments)." (PMID 38699426, 2024). "Other factors associated with oral intake include age, stroke severity, consciousness disturbance, premorbid independence, oral status, low body mass index (BMI), and low serum albumin level." (PMID 38558178, 2024). "Both studies confirm that lower serum albumin levels are associated with more severe stroke (higher NIHSS scores) and worse functional outcomes, supporting albumin's role as a prognostic biomarker in acute ischemic stroke." (PMID 40655892, 2024). "In summary, our MR study has showcased the causal influence of genetically proxied lower levels of serum albumin on the risk of developing stroke, PHD, AF, and VTE." (PMID 38580915, 2024).
Stroke (continued). "Subgroup analyses revealed that serum albumin levels were inversely associated with severe ADL limitations following a stroke in different subgroups, consistent with the primary outcome." (PMID 39835151, 2024). "Our study, for the first time, by using MR method, demonstrated that the higher levels of serum albumin show a causal protective effect on the risk of stroke." (PMID 38580915, 2024). "Lastly, lower albumin concentrations were a risk factor for stroke in patients with hip fracture (MD − 3.18, 95% CI − 4.06 to 2.31)." (PMID 37848510, 2023). "An examination of subgroups revealed that the inverse relationship between serum albumin levels and risk of stroke was statistically significant in men, participants under 60 years old, non-diabetic participants, and hypertensive participants." (PMID 37682189, 2023). "We previously reported that fecal calprotectin had an association with the Glasgow Coma Scale, which is suggestive of gut–brain axis and deficiency of blood albumin and lymphocytes in stroke patients." (PMID 37760793, 2023). "RA is another inflammation biomarker derived from the ratio of RDW to albumin, which was reported to be associated with mortality of stroke." (PMID 36814998, 2023). "Stroke severity was a risk factor and albumin levels >3.5 mg/dL were a protective factor for the incidence of in-hospital complications in patients with acute ischemic stroke." (PMID 37305511, 2023). "According to Pascoe MC, a low serum albumin level after stroke was associated with long-term depression symptoms in elderly Swedish patients." (PMID 36653784, 2023). "Serum albumin levels were significantly and inversely linked with the risk of stroke after controlling for possible variables [odds ratio 0.02, 95% confidence interval (0.00, 0.18), P = .0003]." (PMID 37682189, 2023). "Continuous serum albumin levels (ln transform) were shown to be inversely correlated with the risk of stroke in the crude model [odds ratio (OR) 0.02, 95% confidence interval (CI) (0.01, 0.04), P < .0001]." (PMID 37682189, 2023). "Further research is necessary to determine the fundamental process of this and the therapeutic application of serum albumin amounts to lower stroke risk." (PMID 37682189, 2023). "Stroke severity was a risk factor and albumin greater than 3.5 mg/dL was a protective factor for the incidence of in-hospital complications." (PMID 37305511, 2023). "Our investigation demonstrated a consistent inverse relationship between serum albumin levels and stroke risk." (PMID 37682189, 2023). "A previous study reported that NPAR outperforms NLR and albumin alone in predicting stroke-associated infection." (PMID 37344786, 2023). "In contrast, a significant increase of albumin infiltration was detected in the IL peri-infarct area of stroke brains, reflecting a loss of blood-brain barrier integrity." (PMID 38107410, 2023). "Low serum albumin levels are associated with ischemic heart disease, heart failure, AFib, stroke, and venous thromboembolism." (PMID 37367406, 2023). "An important clinical trial published in Stroke found that relatively low serum albumin level is associated with poor outcome in patients with ischemic stroke." (PMID 37563630, 2023). "An inverse relationship between serum albumin levels and stroke risk was also revealed by smoothing the curve fit." (PMID 37682189, 2023). "This is the first study to show that low albumin levels increase the risk of stroke in patients with hip fracture, although the results should be considered with caution due to the low number of included articles." (PMID 37848510, 2023). "The purpose of this study was to investigate the diagnostic performance of the neutrophil percentage-to-albumin ratio (NPAR) for predicting stroke-associated pneumonia (SAP) and functional outcome in patients with intracerebral hemorrhage (ICH)." (PMID 37388726, 2023).
Stroke (continued). "Many studies have showed the level of albumin was associated with adverse outcomes of many diseases, including heart failure, atrial fibrillation, ischemic heart disease, myocardial infarction, stroke and venous thromboembolism." (PMID 37974066, 2023). "Observational studies suggested that higher serum albumin levels measured within 36 h after stroke onset were associated with a reduced risk of in‐hospital death and 3‐month unfavorable outcomes." (PMID 37287379, 2023). "After adjustment for traditional cardiovascular risk factors, serum albumin levels remained inversely associated with ischemic heart disease, heart failure and stroke." (PMID 36755341, 2023). "Prior studies have suggested that the association between lower albumin and increased risk of death in patients with acute coronary syndrome, stroke and acute heart failure." (PMID 37957767, 2023). "(RR = 1.76; 95% CI, 1.09–2.86; p = 0.022) and albumin levels >3.5 mg/dL which went from 0.45 to 0.53 (RR = 0.53; 95% CI, 0.36–0.79; p = 0.002) were maintained after adjusting for age, sex and stroke risk factors." (PMID 37305511, 2023). "Serum albumin levels were inversely correlated with the risk of stroke in individuals over 40 after controlling for variables using multiple logistic regression, and smoothed curve fitting revealed the same findings." (PMID 37682189, 2023). "Individuals inside the Q4 group had a statistically significant 45% reduced risk of stroke compared to individuals in the Q1 group as a reference [OR 0.55, 95% CI (0.31, 0.98), P = .0414] when serum albumin was transformed to a categorical variable." (PMID 37682189, 2023). "A study has demonstrated that low level of serum albumin is associated with long-term depressive symptoms in stroke surviving elderly individuals." (PMID 34983435, 2022). "Low albumin level was related significantly to poor outcomes among all stroke subtypes and increased risk of recurrence in patients with AIS." (PMID 35405949, 2022). "We found that higher albumin-corrected calcium levels were associated with poor functional outcome in stroke patients after mechanical thrombectomy." (PMID 36056314, 2022). "We measured the serum calcium by inductively coupled plasma mass spectrometry and assessed the associations between serum albumin-corrected calcium and first stroke using conditional logistic regression." (PMID 35989922, 2022). "We further explored the role of other covariables on the association between serum albumin-corrected calcium and first stroke." (PMID 35989922, 2022). "Higher serum albumin-corrected calcium levels are independently associated with revascularization and poor outcome in stroke patients after mechanical thrombectomy." (PMID 36056314, 2022). "From a population of 602 participants, patients with high serum albumin levels at the time of a stroke demonstrated a 71% decreased odds of all-cause mortality compared with normal serum albumin levels OR = 0.29 (95%CI 0.18–0.48, P < 0.0001, I2 = 0%)." (PMID 35640017, 2022). "The LR analysis showed that age, the National Institute Health Stroke Scale score, BI index, hemoglobin, and albumin were independently associated with stroke outcome." (PMID 35544482, 2022). "A number of studies had shown that high ALB levels were associated with better prognosis in stroke patients." (PMID 36567762, 2022). "Consistently, restricted cubic spline showed a U-shaped association between serum albumin-corrected calcium and risk of total stroke and ischemic stroke." (PMID 35989922, 2022). "The associations between serum albumin-corrected calcium and the risk of first stroke in various subgroups*." (PMID 35989922, 2022). "Further analyses using restricted cubic spline confirmed the U-shaped association between serum albumin-corrected calcium and risk of first total stroke and ischemic stroke." (PMID 35989922, 2022).
Stroke (continued). "We aimed to evaluate the association between serum albumin-corrected calcium and the risk of the first stroke in the Chinese community-dwelling population." (PMID 35989922, 2022). "Not only in stroke but serum albumin has been linked with unfavorable vascular events in patients with cardiac and renal diseases." (PMID 33959442, 2021). "A low ALB level, even within the normal range, is associated with myocardial infarction, coronary heart disease, and stroke morbidity and mortality." (PMID 34733230, 2021). "Studies have found that ALB is associated with the occurrence of stroke, and low albumin is often used as one of the indicators to predict poor prognosis after stroke." (PMID 33505489, 2021). "Another study with 220 cardiac surgery patients and a POD incidence of 52% identified four independent risk factors for delirium: MMSE impairment, prior stroke or transient ischemic attack, depression, and abnormal albumin." (PMID 34385913, 2021). "Albumin deficiency is often found in hospitalized patients, and is reported in up to 19% of stroke patients." (PMID 33959442, 2021). "Atrial fibrillation, urinary albumin:creatinine ratio and HbA1c were independently associated with stroke in the most parsimonious model." (PMID 32234054, 2020). "In accordance with the key role of caveolin-1 in caveolae formation, caveolin-1 deficient mice exhibited reduced albumin uptake/transport to the brain parenchyma in the first hours after stroke." (PMID 30523362, 2019). "The analysis revealed that age, a history of AF and stroke severity are correlated with a higher risk of HT, whereas baseline blood platelet, albumin, cholesterol and low-density lipoprotein (LDL) levels are associated with a lower risk of HT." (PMID 30987606, 2019). "Male gender, BMI, ASA classification ≥3, history of stroke, smoking, and serum albumin level < 3.5 g/dL were significant risk factors for dysphagia in the regression analysis without adjustment and were thus included in the multivariate regression model." (PMID 31852457, 2019). "Many studies have demonstrated an inverse relation between the concentration of serum albumin, stroke risk, and functional outcome." (PMID 30046235, 2018). "In recent years, there has been increasing interest in the association between serum albumin levels and stroke." (PMID 30046235, 2018). "Nutritional status is another stroke risk concern in chronic dialysis patients, whose serum albumin levels have been found to be lower than normal." (PMID 29329323, 2018). "As observed in our initial characterisation, rt-PA treatment induced a similar increase in albumin extravasation as seen for vehicle-treated mice but caused a significant upsurge in the brain haemoglobin content measured 24 h after stroke (p < 0.05)." (PMID 29157263, 2017). "A lowered albumin concentration, as observed in the blood of smokers, is connected with a higher risk of stroke and coronary heart disease." (PMID 27548057, 2016). "Other independent risk factors of stroke were lower albumin-corrected calcium in HD patients and higher triglycerides in PD patients." (PMID 26485155, 2015). "In the univariate model (model 1), obviously reduced salivary flow rate was significantly associated with age, medical history of stroke, serum albumin levels, dental prosthetic status, plaque score, and periodontal status." (PMID 25705657, 2015). "Multivariate Cox regression analysis revealed that basin group, serum albumin levels, and the complications of stroke and CAD were significant risk factors for 2-year mortality in these patients." (PMID 24058552, 2013). "Lower education level, arthritis, stroke, congestive heart failure, and cancer were associated with a higher odds of worse self-reported limitation, while a higher level of serum albumin was associated with a lower odds of a worse self-reported limitation." (PMID 20707890, 2010).
Stroke (continued). "Finally, low serum albumin levels decrease red blood cell deformability, increasing blood viscosity and further elevating stroke risk." (PMID 40491586, 2025). "The ratio of red blood cell distribution width (RDW) to albumin (ALB) (RAR) has been associated with poor outcomes after stroke, but its role in AMIS remains unclear." (PMID 40720528, 2025). "Additionally, they also found that low albumin levels were significantly associated with poor prognosis in all subtypes of stroke etiology according to TOAST (Trial of ORG 10172 in Acute Stroke Treatment)." (PMID 40248032, 2025). "The findings of this study align with prior research that has identified critical risk factors for HT, such as AF, NIHSS score, and elevated ALB levels, while also offering new insights into the protective roles of specific vascular and stroke subtype characteristics." (PMID 40697574, 2025). "Second, low serum albumin leads to impaired fibrinolysis and reduced platelet aggregation, promoting the formation of atherosclerotic plaques or blood clots, thus increasing the risk of stroke." (PMID 40491586, 2025). "Previous studies indicated that low serum ALB levels are associated with stroke." (PMID 40799261, 2025). "Similarly, indices like the fibrinogen-to-albumin ratio (FAR) have shown associations with stroke risk in small vessel disease, supporting the prognostic relevance of albumin-based markers in cerebrovascular pathology." (PMID 40917659, 2025). "In several studies, ALB was involved as a key factor for stroke risk and prognosis." (PMID 40371078, 2025). "Reduced albumin levels have been strongly associated with poor outcomes in stroke patients." (PMID 39935611, 2025). "Both studies find that serum albumin levels are significantly associated with stroke outcomes." (PMID 40655892, 2024). "Furthermore, our systematic review and meta-analysis, provides the most comprehensive analysis to date and is the first to report pooled effect sizes of albumin per quartile group, providing a nuanced understanding of its association with post-stroke outcomes." (PMID 38794724, 2024). "This study demonstrates that albumin levels on admission after ischemic stroke may help stratify long-term risk of adverse stroke outcomes and identify patients who can benefit from stricter monitoring." (PMID 38794724, 2024). "However, the specific appropriate dosage of albumin to reduce stroke risk requires longer follow-up trials for verification." (PMID 39483787, 2024). "Meanwhile, Serum albumin levels and the risk of stroke were negatively correlated." (PMID 39835151, 2024). "A study conducted on a sample of 307 patients who had suffered from ischemic stroke (with a mean age of 63 years) revealed that low serum pre-albumin levels at admission were linked to post-stroke depression reported 30 months following the onset of the stroke." (PMID 38355455, 2024). "The aim of this study was to evaluate the associations between albumin levels during the first 24 hours after an ischemic stroke and the 30-day risk of cardiovascular events or death in a large cohort of patients with stroke from a federated health research network." (PMID 38323429, 2024). "Hence, we posited that there was an inverse relationship between albumin levels and the risk of all-cause mortality in stroke patients." (PMID 38699426, 2024). "Reduced blood albumin levels are associated with poor dietary status and chronic inflammation, and these factors may affect the outcome of stroke." (PMID 38846203, 2024). "An increased risk of stroke was linked to lower serum albumin levels." (PMID 37682189, 2023). "We investigated the link between serum albumin levels and stroke risk in persons above 40 years of age to see if there is any correlation between them using a cross-sectional analysis of a nationally representative National Health and Nutrition Examination Survey-based dataset." (PMID 37682189, 2023).